APP (amyloid beta precursor protein)
Diseases named in the same sentence as APP in open-access papers (continued):
Sharing a sentence is not in itself a finding about the gene and the disease.
Alzheimer disease (continued). "The trans-membranous protein amyloid precursor protein (APP) has been intensely studied in Alzheimer's disease (AD), since it is the source of β-amyloid (Aβ) peptides, recognized as key-components in AD pathophysiology." (PMID 20569437, 2010). "Generation of the amyloid β (Aβ) peptide of Alzheimer's disease (AD) is differentially regulated through the intracellular trafficking of the amyloid β precursor protein (APP) within the secretory and endocytic pathways." (PMID 21192821, 2010). "APP is mostly known for being the source of the toxic amyloid-β (Aβ) peptide found in neuritic plaques of Alzheimer's disease (AD) patients." (PMID 20932279, 2010). "Our results depicted overt cardiomyocyte mechanical dysfunction in the APP/PS1 Alzheimer's disease model, possibly due to oxidative stress." (PMID 19551139, 2009). "The APP/PS1 mouse model used in our study possesses concurrent mutated forms of APP and Presenilin 1 (PS1), both identified separately in human Alzheimer diseases." (PMID 19551139, 2009). "Recent advances in the understanding of the generation of amyloid in Alzheimer's disease has lead to the finding that BRI2 interacts with the Amyloid Precursor Protein (APP), decreasing the efficiency of APP processing to generate Aβ." (PMID 19924302, 2009). "One such protein is APPL, the functional Drosophila homologue of the mammalian Amyloid precursor protein (APP) that is encoded by one of the causative genes in Alzheimer's disease." (PMID 19209226, 2009). "The Alzheimer disease (AD) amyloid protein precursor (APP) can bind the FE65 adaptor protein and this complex can regulate gene expression." (PMID 19343227, 2009). "In a transgenic mouse model of Alzheimer disease (AD), cleavage of the amyloid precursor protein (APP) by the α-secretase ADAM10 prevented amyloid plaque formation, and alleviated cognitive deficits." (PMID 19196476, 2009). "The formation of the amyloid-β peptide (Aβ) from the Aβ precursor protein (APP) is a critical molecular event in the pathogenesis of Alzheimer's disease (AD)." (PMID 19090992, 2008). "Amyloid beta precursor protein is a cell surface protein with signal-transducing properties, and it is thought to play a role in the pathogenesis of Alzheimer's disease." (PMID 18698424, 2008). "With amyloid precursor protein (APP) variants (the Swedish- and London-type variants) related to familial Alzheimer's disease as model disease alleles, we were able to determine competent siRNA duplexes conferring ASP-RNAi." (PMID 18493311, 2008). "Recently, a promising Aβ vaccine strategy was employed in transgenic amyloid precursor protein (APP) mice as a model for Alzheimer's disease." (PMID 18167537, 2008). "Advanced age and mutations in the genes encoding amyloid precursor protein (APP) and presenilin (PS1) are two serious risk factors for Alzheimer's disease (AD)." (PMID 18716656, 2008). "A number of studies have shown that increased APP levels, resulting from either a genomic locus duplication or alteration in APP regulatory sequences, can lead to development of early-onset dementias, including Alzheimer's disease (AD)." (PMID 18684319, 2008). "The amyloid precursor protein (APP) was assumed to be an important neuron-morphoregulatory protein and plays a central role in Alzheimer's disease (AD) pathology." (PMID 18648492, 2008). "The abnormal processing of the amyloid precursor protein (APP) is a pivotal event in the development of the unique pathology that defines Alzheimer's disease (AD)." (PMID 18178006, 2008). "The generation of the amyloid-β peptide (Aβ) through the proteolytic processing of the amyloid precursor protein (APP) is a central event in the pathogenesis of Alzheimer's disease (AD)." (PMID 17620134, 2007). "This study suggests a possible role for APP in normal cognitive ageing, in addition to its role in Alzheimer's disease." (PMID 17601350, 2007).
Alzheimer disease (continued). "A central event in Alzheimer's disease (AD) is the regulated intramembraneous proteolysis of the β-amyloid precursor protein (APP), to generate the β-amyloid (Aβ) peptide and the APP intracellular domain (AICD)." (PMID 17718916, 2007). "Following ectodomain cleavage of the amyloid precursor protein (APP) by β-secretase, γ-secretase cleavage releases the amyloid beta peptide (Aβ) that accumulates in the brains of patients with Alzheimer's disease (AD)." (PMID 16930450, 2006). "Previous studies have shown that in platelets of mild Alzheimer Disease (AD) patients there are alterations of specific APP forms, paralleled by alteration in expression level of both ADAM 10 and BACE when compared to control subjects." (PMID 16048651, 2005). "As most Alzheimer disease cases occur well past midlife, the current study examined adoptive transfer of anti-Aβ antibodies to 19- and 23-month old APP-transgenic mice." (PMID 15588287, 2004). "Synaptic vesicle glycoprotein 2A, the newly identified APP‐binding protein, reduces amyloid‐β plaque deposition in Alzheimer's disease by suppressing the amyloidogenic pathway through inhibition of BACE1‐APP interaction and alteration of APP endosomal‐lysosomal localization." (PMID 41521688, 2026). "Interestingly, the APP gene, which plays a significant role in Alzheimer disease pathology, is located on chromosome 21 (21q21.3)." (PMID 40333415, 2025). "This increased risk is due to the presence of an extra copy of chromosome 21 in these individuals, which contains the gene for amyloid precursor protein (APP), leading to increased production and accumulation of amyloid-beta and increased risk of Alzheimer’s disease at relatively younger ages." (PMID 41465426, 2025). "These include studies involving familial Alzheimer’s disease causing mutants of Presenilin-1 and − 2 and the amyloid precursor protein (APP), and studies on the effects of ε4 allele of apolipoprotein E (ApoE4) which is a major risk factor for Alzheimer’s disease." (PMID 40045432, 2025). "The 30 days course of oral administration of a semipurified extract of Withania somnifera was reported to inhibit the aggregation of Aβ proteins in the brains of middle-aged and old APP/PS1 Alzheimer’s disease transgenic mice through enhanced clearance of the protein." (PMID 40305223, 2025). "In Alzheimer's disease, flotillins are involved in amyloid precursor protein (APP) processing and trafficking, and their dysregulation might lead to the accumulation of beta amyloid (βA) plaques." (PMID 39877933, 2025). "Additionally, Yingying Xu utilized pyrosequencing to examine changes in mtDNA methylation within the CYTB and COX II genes in the hippocampus of APP/PS1 transgenic mice with Alzheimer’s disease." (PMID 40689209, 2025). "Results from animal experiments indicate that intranasal administration of hyperoside (at doses of 20, 40, and 80 mg/kg, administered once every 3 days for 8 weeks) significantly improved cognitive function and motor coordination in APP/PS1 double-transgenic Alzheimer’s disease mice." (PMID 40098612, 2025). "In addition, this model has been proposed as a valuable tool for Alzheimer’s disease research due to the close homology between the amyloid precursor protein (APP) of chick and humans." (PMID 40822853, 2025). "Studies have demonstrated that the TCM formula Jinsiwei(GAPT) exhibited the ability to improve learning and memory abilities in APP/PS1 Alzheimer’s disease (AD) mouse models by reducing the expression of phosphorylated Tau (P-Tau) and increasing the expression of P-AKT and P-AKT/AKT." (PMID 40166467, 2025). "The changes in the intracellular and extracellular contents of APP isoforms may promote Alzheimer’s disease." (PMID 39851568, 2025). "Indeed, among the cargos of the flotillin‐mediated endocytic route, several proteins are deregulated in Alzheimer's disease, particularly APP, and in Parkinson's disease, particularly DAT, glutamate transporter, and α‐synuclein." (PMID 39877933, 2025).
Alzheimer disease (continued). "We identified 14 Alzheimer’s disease-related genes that were expressed in the prefrontal cortex (e.g., APP and APOE) and 55 RIKEN bioresources, which were genetically modified mice related to these genes, predicted to be relevant to Alzheimer’s disease research." (PMID 40380154, 2025). "Finally, Dickkopf-1, which plays a key role in synaptic and neuronal dysfunction in Alzheimer’s disease, was strongly induced at lesion sites in male APP/PS1 mice, whereas its induction was reduced in females." (PMID 40724648, 2025). "Notably, MMEJ editing of APP produces a C-terminal truncation shown to be protective against Alzheimer’s disease, and we observe this particular 5-bp MMEJ result with Cas9-d in our iPSC-neurons." (PMID 40799508, 2025). "Moreover, the APP gene is well known to have a role in Alzheimer’s disease, making it a clinically relevant gene to target for CNS applications." (PMID 40799508, 2025). "In this review, I aim to summarize what is currently known about the relationship between iron homeostasis and the IRE in the 5’UTR of APP mRNA, as well as how these molecules may be used for therapeutic and clinical purposes in Alzheimer’s disease." (PMID 40438504, 2025). "Indeed, Down syndrome, characterized by the triplication of the APP gene, represents a valuable genetic model for studying early-onset Alzheimer's disease and accelerated aging." (PMID 40536952, 2025). "Down syndrome–Alzheimer’s disease (DSAD) is the most commonly occurring single genetic cause of AD, and is in part a result of triplication of the amyloid precursor protein gene (APP) on Hsa21, which results in the increased production of the amyloid-β peptide and other APP gene products." (PMID 40387921, 2025). "Familial Alzheimer’s disease (FAD) is caused by dominant missense mutations in amyloid precursor protein (APP) and presenilin-1 (PSEN1), the catalytic component of γ-secretase that generates amyloid β-peptides (Aβ) from the APP C-terminal fragment C99." (PMID 40723827, 2025). "This study provides the first in vivo evidence that APP deletion has profound and detrimental effects on both amyloid and tau pathologies in a transgenic model of Alzheimer’s disease, highlighting the previously unappreciated role of APP in the regulation of these neurodegenerative processes." (PMID 40001463, 2025). "Enlarged endosomes have been observed in Alzheimer’s disease, together with an accumulation of APP, and endosome enlargement may also result in perturbation of Golgi morphology by reduced membrane flow from defects in retrograde transport." (PMID 40302938, 2025). "It was initially hypothesized that brain microinfarcts play a crucial role in the early development of Alzheimer’s disease-like pathology in a sex-dependent manner in young APP/PS1 mice." (PMID 40724648, 2025). "In Alzheimer’s disease, Aβ is derived from the amyloid precursor protein (APP)." (PMID 40077524, 2025). "Thus, the APBB2 gene plays a significant role in APP processing and Alzheimer’s disease pathogenesis." (PMID 40733561, 2025). "The oxidative stress produced by dysfunctional mitochondria in microglia generates abundant reactive oxygen species (ROS), which activate BACE-1 leading to amyloid precursor protein (APP) cleavage into Aβ (amyloid-beta), contributing to Alzheimer's disease pathology." (PMID 40585705, 2025). "Studies on Alzheimer’s disease have shown that mice with BBB-specific GLUT1 deficiency exhibit reduced cerebral microvascular degeneration, decreased cerebral blood flow, and accelerated APP deposition." (PMID 39981435, 2025). "For example, in Alzheimer’s disease, the lactylation of the amyloid precursor protein (APP) at the K612 site affects its metabolic pathway, inhibits the amyloid pathway, promotes the endosomal–lysosomal degradation pathway, and reduces the production of the pathological deposition of amyloid-β (Aβ)." (PMID 40724863, 2025).
Alzheimer disease (continued). "Intriguingly, certain cognitive impairment models, such as APP/PS1 mice with early‐stage Alzheimer's disease, also show hyperactivity characterised by increased total movement in the open field, despite maintained short‐term memory and anxiety‐related behaviour." (PMID 41318982, 2025). "APP contributes to age‐related neurodegenerative changes by disrupting the expression of synapse‐related genes via histone deacetylase (HDAC) regulation, thereby accelerating memory loss in Alzheimer's disease." (PMID 41323819, 2025). "Furthermore, miR-149-5p-mediated KAT8 suppression reduced global H4K16ac levels in 293/APPsw cells, leading to decreased soluble amyloid beta precursor protein (APP) beta peptide production and potentially attenuating Alzheimer’s disease progression." (PMID 40508066, 2025). "One of the distinctive features of Alzheimer's disease is the presence of amyloid plaques composed of aggregated amyloid b (Ab) peptides that result from the sequential cleavage of the amyloid precursor protein (APP)." (PMID 40552310, 2025). "Moreover, aberrant deubiquitination of α-synuclein, tau, and amyloid precursor protein (APP) by USP8 is intimately linked to the onset and progression of neurodegenerative disorders such as Parkinson’s and Alzheimer’s diseases." (PMID 41301681, 2025). "Aβ is derived from the amyloid precursor protein (APP), and as a sticky protein, Aβ clumps together and forms amyloid plaques that disrupt cell function in the brain, with such plaques being a pathological hallmark of Alzheimer’s disease." (PMID 40433620, 2025). "Additional targets such as APP (amyloid precursor protein) implicate potential connections to Alzheimer’s disease pathology, while MMP9 (matrix metalloproteinase-9) may modulate extracellular matrix remodeling and blood–brain barrier integrity." (PMID 40943635, 2025). "Understanding the intricate mechanisms and molecular players involved in APP processing substantially enhances our knowledge of Alzheimer’s disease pathology and holds promise for the development of biomarkers of ongoing pathology at the earliest stages of Alzheimer’s disease." (PMID 40722590, 2025). "Amyloid precursor protein (APP) plays a key role in the pathogenesis of Alzheimer’s disease (AD)." (PMID 41023583, 2025). "The role of APP in the pathogenesis of Alzheimer’s disease (AD) has been extensively investigated." (PMID 40927393, 2025). "Given the similarities between canine cognitive dysfunction syndrome (CDS) and Alzheimer’s disease (AD) in humans, particularly in amyloid precursor protein (APP) processing, amyloid plaque deposition, and cognitive impairment, studies have investigated shared pathophysiological markers." (PMID 40646873, 2025). "We explored how the phosphorylation state of collapsin response mediator protein 2 (CRMP2) influences mitochondrial functions in cultured cortical neurons and cortical synaptic mitochondria isolated from APP-SAA KI mice, a knock-in APP mouse model of Alzheimer’s disease (AD)." (PMID 40358171, 2025). "APP also plays a key role in the pathogenesis of Alzheimer's disease (AD)." (PMID 41023583, 2025). "The accumulation and aggregation of amyloid beta (Aβ)—a peptide fragment derived from the proteolytic processing of amyloid precursor protein (APP)—is a central pathological feature of Alzheimer’s disease (AD) and a current target for disease-modifying therapies." (PMID 40671818, 2025). "These technologies, including whole-exome sequencing (WES) and whole-genome sequencing (WGS), have facilitated the identification of pathogenic mutations in genes such as APP, PSEN1, and PSEN2 in Alzheimer’s disease (AD), as well as LRRK2, SNCA, and PINK1 in Parkinson’s disease (PD)." (PMID 40076852, 2025).
Alzheimer disease (continued). "Initially identified for its role in Alzheimer disease (AD) via the production of amyloid-beta (Aβ) peptides, a key component of amyloid plaques, APP is now recognized as a multifunctional protein involved in synaptic plasticity, axonal transport, neuronal migration, and intracellular signaling." (PMID 40817583, 2025). "The GSAP was identified as a γ-secretase-interacting partner, it could form a complex with γ-secretase and APP-CTF, and an SNP in GSAP has been discovered to be associated with Alzheimer’s disease, giving genetic evidence that links GSAP to AD susceptibility." (PMID 40927393, 2025). "Interestingly, highly connected nodes included APP (amyloid beta precursor protein) and HTT (huntingtin), commonly associated to Alzheimer’s disease and Huntington’s disease, respectively." (PMID 39119577, 2024). "Also, oxidative stress, one of the important factors in aging‐related Alzheimer's disease, leads to the cleavage of the amyloid precursor protein (APP) and amyloid beta (Aβ) production/accumulation, accelerating the occurrence of CI." (PMID 39135287, 2024). "Additionally, mutations in the amyloid precursor protein (APP), presenilin 1 (PSEN1), and presenilin 2 (PSEN2) genes have been identified in patients with an autosomal-dominant form of early-onset Alzheimer’s disease." (PMID 38926887, 2024). "In addition, NSG1 and NSG3 regulate proteolytic processing of Neuregulin-1 and Amyloid Precursor Protein (APP), genes that play critical roles in Schizophrenia and Alzheimer’s Disease, respectively." (PMID 39257983, 2024). "Characteristic cerebral pathological changes of Alzheimer’s disease (AD) such as glucose hypometabolism or the accumulation of cleavage products of the amyloid precursor protein (APP), known as Aβ peptides, lead to sustained endoplasmic reticulum (ER) stress and neurodegeneration." (PMID 38464180, 2024). "Alzheimer’s disease is characterized by an extracellular deposition of the amyloid b peptide (Aβ) that exists in different forms after the cleavage of the amyloid protein precursor (APP)." (PMID 38257833, 2024). "Moreover, using mouse model of Alzheimer's disease, CC treatment promoted clearance of amyloid-β plaques and ameliorated cognitive function in both 7- and 3-month-old APP/PS1 mice." (PMID 39454957, 2024). "In addition, Akk has been shown to attenuate cognitive impairment and brain amyloid-beta deposition in an APP/PS1 mice model of Alzheimer’s disease." (PMID 38539626, 2024). "In Alzheimer's disease (AD), characterized by the presence of amyloid-beta (Aβ) plaques and tau protein tangles, critical genetic factors include the amyloid precursor protein (APP), presenilin 1 (PSEN1), presenilin 2 (PSEN2), and apolipoprotein E (APOE)." (PMID 39411638, 2024). "miR-129-5p has been suggested to play roles in Alzheimer’s disease, potentially involving the regulation of autophagy, neuroinflammation, and neuronal cell death through targeting amyloid precursor protein (APP), high-mobility group box 1 (HMGB1), and yes-associated protein 1 (YAP1) genes." (PMID 38195609, 2024). "By employing source-reconstructed MEG in cognitively unimpaired individuals carrying mutations in the APP and PSEN1 genes, this study aimed to provide increased insights on quantitative neurophysiological alterations during a true early stage of Alzheimer’s disease." (PMID 39713236, 2024). "ACY-738 administration improved axonal transport, reduced hyperphosphorylated tau and improved performance in contextual fear conditioning, and open field performance in the APP/PS1 murine model of Alzheimer's disease and improved short-term memory in an in vivo multiple sclerosis model." (PMID 39130445, 2024). "In Alzheimer’s disease, disrupted copper homeostasis contributes to disease progression by promoting the formation of toxic amyloid-beta oligomers and interacting with amyloid precursor protein (APP)." (PMID 39596378, 2024).